IGF1R (insulin like growth factor 1 receptor)
Diseases named in the same sentence as IGF1R in open-access papers (continued):
Sharing a sentence is not in itself a finding about the gene and the disease.
gastric cancer (continued). "Therefore, the effect cannot be explained by off-target effects, e.g., by cetuximab binding and paradoxical stimulation of Insulin-like growth factor 1 receptor, a mechanism that has been proposed in the context of cetuximab resistance in gastric cancer." (PMID 32039027, 2019). "We demonstrated that IGF-1R expression was correlated with prognosis and OS in gastric cancer." (PMID 31318186, 2019). "This study aimed to describe the prognostic importance of epidermal growth factor (EGFR), phosphatase and tensin homolog (PTEN), human EGF receptor-2 (HER-2), and insulin-like growth factor 1 receptor (IGF-1R) in gastric cancer patients treated with postoperative chemoradiation therapy." (PMID 31318186, 2019). "In our study, 24 of 69 cases (34.8%) of gastric cancer were positive for IGF-1R expression." (PMID 31318186, 2019). "Furthermore, promoter regions of IGF1 were concomitantly demethylated upon treatment of 5-AzaC, supporting promoter hypomethylation as one of the mechanisms for activation of the IGF1/IGF1R pathway in gastric cancer." (PMID 29725014, 2018). "Since our data indicated that benefit of inhibiting IGF1/IGF1R pathway might be limited to MP subtype gastric cancer, possible reasons for current failure might be due to the lack of use of patient enrichment by biomarkers in the trials." (PMID 29725014, 2018). "We next tested if MP gastric cancer cells were more sensitive to inhibition of IGF1R." (PMID 29725014, 2018). "Although relatively few gastric cancer cases have been evaluated, one report demonstrated that IGFIR overexpression in a primary tumor was correlated with increased lymph node metastasis, and that patients with low expression of both IGF1R and EGFR had significantly improved OS." (PMID 26884344, 2017). "Our previous study demonstrated that PKG II could inhibit the activation of some key members of the RTK family, including EGFR, VEGFR, PDGFR and IGF-1R, and the consequent signal transduction in gastric cancer cells." (PMID 27147579, 2016). "And our unpublished data also indicated that miR-122, as well as IGF-1R knockdown could significantly inhibit cell proliferation, migration and invasion in gastric cancer cells." (PMID 27486823, 2016). "Targeting the miR-7/IGF1R/Snail axis may be useful as a therapeutic approach for blocking gastric cancer metastasis." (PMID 24137382, 2013). "Additionally, 1 hindered the progression of gastric cancer by inhibiting the SUMOylation of IGF-1R." (PMID 34944537, 2021). "Here, we report that gastric cancers with a mesenchymal phenotype are associated with poor prognosis, markedly low somatic mutation rates and microsatellite instability (MSI), resistance to standard chemotherapy, and sensitive to inhibition of IGF1/IGF1R pathway." (PMID 29725014, 2018). "Another example is insulin-like growth factor-1 receptor (IGF-1R), it was frequently expressed in gastric cancers and was associated with tumor size, quantity of stroma, depth of wall invasion, lymph node metastasis, TNM stages and differentiation status of gastric cancer." (PMID 20529313, 2010). "Among these agents, inhibitors targeting IGF-1R (BMS-754807) and the PI3K-mTOR pathways (AZD8186, AZD8055) emerged as the most promising candidates for therapeutic intervention in gastric cancer." (PMID 38962317, 2024). "On the other hand, miR-206 mediates the regulation of c-MET, IGF1R, and MAPK3’s expression in gastric cancer." (PMID 38200584, 2024). "The dysregulation of LHPP expression leads to the upregulation of IGF1R, thereby activating the downstream ITGB1–FAK–SRC/YAP–c‐MYC signaling pathway, resulting in the development and progression of gastric cancer." (PMID 38292328, 2024). "Activation of the IGF1R/IRS1 pathway has also been identified to promote drug resistance of multiple malignancies, including gastric cancer." (PMID 32192494, 2020). "In gastric cancer, IGF1/IGF1R/STAT3 signaling‐inducible IFITM2 promotes gastric cancer growth and metastasis." (PMID 32851683, 2020).
gastric cancer (continued). "The present study was designed to define the prognostic importance of HER-2, IGF-1R, PTEN, and EGFR in gastric cancer patients treated with postoperative chemoradiation therapy." (PMID 31318186, 2019). "MiR-99b-5p inhibited the proliferation by negatively regulating the insulin-like growth factor 1 receptor (IGF-1R) and activating the AKT signaling pathway in gastric cancer." (PMID 31750241, 2019). "Reduced miR-7 expression dramatically enhances growth, invasion, and metastasis of cancer cells and contributes to gastric cancer development and progression by targeting Epidermal Growth Factor Receptor (EGFR) or insulin-like growth factor-1 receptor." (PMID 31200531, 2019). "In conclusion, this study suggests that IGF-1R, EGFR, and cigarette smoking can be used as additional prognostic factors to the previously known prognostic factors in gastric cancer patients treated with chemoradiation therapy." (PMID 31318186, 2019). "In our study, we demonstrated that the IGF‐1R‐related pathway dependency of both proliferation and invasion was changed by EBV infection in a gastric cancer cell line." (PMID 30247804, 2018). "Our unpublished data indicated that the expression IGF-1R, a target of miR-122 was positively correlated with the expression of MALAT1 in gastric cancer cell lines." (PMID 27486823, 2016). "IGF2BP2 activates the RhoA-ROCK pathway by recognizing the m6A methylation site on insulin-like growth factor 1 receptor(IGF1R) mRNA, enhancing the proliferation, migration, and invasion of gastric cancer cells while reducing their tendency to undergo apoptosis." (PMID 39791162, 2025). "Subsequently, to further explore the potential targets involved in the hypoxia-driven metastasis of gastric cancer, we hypothesized that RMP and IGF1r could be targets of miR-598-3p based on the intersection of the 4 gene sets shown in the Venn diagrams." (PMID 38491378, 2024). "Furthermore, the expression of miR-598-3p, IGF1r, and RMP was conducted in a cohort comprising 20 cases of gastric cancer." (PMID 38491378, 2024). "Shoumin Zhu and colleagues conducted a series of in vitro assays and 3D gastric organoid cultures using mouse models and human tissues to determine the effect of DARPP-32 on the activation of IGF1R and STAT3 signaling, which is crucial for the onset of gastric cancer." (PMID 39309860, 2024). "IGF1/IGF1R/STAT3 signaling promoted IFITM2 expression and gastric cancer growth and metastasis." (PMID 32851683, 2020). "A recent genomic study of gastric cancers identified somatic copy number alterations of seven oncogenes involved in tyrosine kinase/MAP-kinase pathways: KRAS, EGFR, HER2, FGFR1, FGFR2, MET and IGF1R." (PMID 27437872, 2016). "We showed that phosphorylation of IGF-1R proteins was up-regulated, indicating that activation of the IGF-1R signaling pathways might be involved in the resistance of gastric cancer to trastuzumab." (PMID 26108989, 2015). "Moreover, cetuximab therapeutically blocks EGFR, and this might concurrently induce the activation of IGF-1R, which could activate EGFR-downstream Akt signaling, thus mediating cetuximab resistance in gastric cancer cells." (PMID 37519889, 2023). "Thus, the PTEN gene might be a factor in the trastuzumab resistance of gastric cancer, and its downstream PI3K-AKT and bypass IGF-1R signaling pathways might be new targets for clinical research on drug resistance in the future." (PMID 26108989, 2015). "Finally, we found that the levels of IGF1-R protein were not affected despite IGF1-R having previously been shown to be a target of miR-7 in gastric cancer and tongue squamous carcinoma cells." (PMID 23762407, 2013). "In addition, elevated Gal-9 expression suppressed proliferation and triggered apoptosis of gastric cancer cells by inducing caspase-cleaved keratin 18 (CCK18) and reducing vascular endothelial growth factor receptor-3 (VEGFR-3) and insulin-like growth factor-1 receptor (IGF-1R) expression." (PMID 40869319, 2025).
gastric cancer (continued). "However, the role of IGF-1R expression is not clearly defined in gastric cancers." (PMID 31318186, 2019). "We concluded that IGF1R and AREG are prognostic, not predictive, markers of stage II/III gastric cancer." (PMID 26884344, 2017).
sarcoma (94 papers, 2009 to 2026). A usually aggressive malignant neoplasm of the soft tissue or bone. "The significance of p-RPS6 in these sarcoma cell lines is underlined by their sensitivity to the IGF1R inhibitor BMS-536924." (PMID 35008473, 2021). "Nuclear IGF-1R is associated with proliferation of alveolar rhabdomyosarcoma cells and contributes to chemoresistance in sarcomas and hepatocellular carcinoma." (PMID 33584548, 2020). "Our results support future clinical trials in high risk sarcomas using SB modified CAR T cells targeting IGF1R and ROR1." (PMID 26173023, 2015). "There is also evidence that nuclear IGF‐1R associates with response to IGF‐1R antibody therapy in patients with sarcoma, suggesting that nuclear IGF‐1R indicates IGF dependence and could be a potential biomarker for response to IGF‐axis targeting treatments." (PMID 41028981, 2025). "Additionally, Akt signaling has been linked to resistance to IGF1 receptor (IGF1R) and mTOR (mammalian target of rapamycin) inhibitors in sarcoma, further demonstrating the role of Akt in tumor survival." (PMID 26402468, 2015). "In addition, increased IGF1R nuclear localization was associated with better overall survival in sarcoma patients treated with IGF1R antibody." (PMID 24904527, 2014). "Evaluation of the anti-IGF1R mAb R1507 efficacy in 23 synovial sarcoma patients showed 4 cases (17%) of disease stabilization as best response, while the mAb figitumumab was associated with one patient experiencing disease stabilization among 13 patients with multiple sarcoma subtypes." (PMID 34440844, 2021). "A phase I study combining temsirolimus (mTOR inhibitor) with cixutumumab (IGF-1R antibody) showed tolerability and early efficacy signals in pediatric sarcomas, including RMS." (PMID 40821216, 2025). "We chose bFGF and EGF, both widely used in organoid protocols, and IGF1, as the IGF1R pathway plays a crucial role in EwS and other sarcoma entities." (PMID 40841513, 2025). "Elevated levels of IGF1R and its ligands have been observed in various sarcomas and it correlates with poor prognosis." (PMID 38434982, 2024). "The combination of rapamycin with the anti-IGF1 receptor (IGF1R) MAB cixutumumab (IMC-A12) demonstrated therapeutic enhancement in some sarcoma models." (PMID 39510293, 2024). "A recent study evaluated IGF1R-targeted CAR-T cells in sarcomas and found that IGF1R-targeted CAR-T cells remarkedly reduced tumor growth in pre-established, localized, and systemically disseminated OS mouse models." (PMID 34503279, 2021). "One in vitro study has shown an indirect link between RON and rpS6 in sarcoma cells, but only upon the development of resistance to an IGF1R inhibitor." (PMID 30456298, 2018). "In contrast, 10/28 sarcoma patients treated with figitumumab, another IGF-1R mAB, had stable disease (SD) or PR." (PMID 29843755, 2018). "Overall, the results are in contrast with the common view of IGF-1R as a marker of aggressiveness; however, previous studies of sarcomas and carcinomas reported similar results." (PMID 28545426, 2017). "Specifically, patients with advanced sarcoma achieved prolonged free survival upon IGF1R monoclonal antibody therapy when IGF1R was present only in the nucleus compared to patients with mixed IGF1R localization." (PMID 28945762, 2017). "Many sarcoma subtypes are characterized by potential driver kinases such as c-Met, IGF1-R, PDGFRα, and c-Kit." (PMID 26675259, 2016). "Mutation and/or overexpression of many receptor tyrosine kinases (RTKs) including c-Met, PDGFR, c-Kit and IGF1-R drive defective signaling pathways in sarcomas." (PMID 26675259, 2016). "Detailed phosphoproteomic analysis from cell lines and patient tumors also revealed involvement of RTKs such as PDGFR, Eph receptors, Axl, c-Met and IGF1-R as potential driver kinases in sarcomas." (PMID 26675259, 2016).
sarcoma (continued). "In a heterogeneous group of sarcoma patients, a combination of an IGF1R antibody and mTOR inhibitor has been shown to have clinical activity but the level of IGF1R expression was not predictive for response." (PMID 27418340, 2016). "Other attempts have been made in identifying renal cell carcinomas that are responsive to mTor inhibitors and sarcomas that are responsive to IGF1R inhibitors." (PMID 27509178, 2016). "The most common RTKs with high basal expression levels in the sarcoma cell lines tested were IGF1-R, c-Kit, c-Met and PDGFRb." (PMID 26675259, 2016). "Good examples include the use of mTor inhibitors in renal cell carcinomas, epidermal growth factor receptor (EGFR) and PDL1 inhibitors in non-small cell lung carcinoma and the experimental use of insulin growth factor-1 receptor (IGF1R) inhibitors in sarcomas." (PMID 27509178, 2016). "Clinical trials to test the safety and efficacy of IGF1R antibodies, sometimes in combination with an mTOR inhibitor, have been performed in sarcoma patients, but only two trials enrolled chondrosarcoma patients." (PMID 27418340, 2016). "Supporting this concept, the tumors of sarcoma patients who derived benefit from therapeutic IGF-1R antibody were reported to show exclusively nuclear IGF-1R." (PMID 27200287, 2016). "Studies in a small group of patients with sarcomas treated with several IGF-1R monoclonal antibodies found that exclusive nuclear IGF-1R was associated with better PFS and PS." (PMID 26217584, 2015). "Mock T cells or CAR T cells co-cultured with ROR1- K562 cells did not release cytokines whereas IGF1R CAR T cells co-cultured with IGF1R+/- K562 cells produced a low level of cytokines compared to IGF1R+ sarcomas." (PMID 26173023, 2015). "Aberrant ALK and IGF-1R signaling have been demonstrated to contribute to oncogenic transformation in pediatric sarcomas and the involvement of IGF-1R signaling in resistance to HDACi was reported in NSCLC." (PMID 26571493, 2015). "IGF1R CAR T cells from two donors also killed a panel of sarcomas lines including 1 EWS (Rh1), 1 OS (SaOS2), 1 FS (HT1080), 3 ARMS (Rh18, Rh30, Rh41) and 2 ERMS (RD, Rh36) (vs K562, p = 0.001)." (PMID 26173023, 2015). "This study was designed to evaluate chimeric antigen receptor (CAR) T cells targeting the type I insulin-like growth factor receptor (IGF1R) or tyrosine kinase-like orphan receptor 1 (ROR1) molecules for their therapeutic potential against sarcomas." (PMID 26173023, 2015). "IGF-1R overexpression has been consistently shown in multiple types of cancer, including pediatric and epithelial cancer and sarcomas." (PMID 26217584, 2015). "The transduced sarcoma lines were recognized as efficiently as the parent lines by patient 1 IGF1R and ROR1 CAR T cells." (PMID 26173023, 2015). "We employed a time-dynamic bioluminescent imaging (BLI) technique in live mice to assess the anti-sarcoma effect of SB-engineered IGF1R and ROR1 CAR T cells." (PMID 26173023, 2015). "In conclusion, our results have demonstrated in vitro and in vivo anti-sarcoma activity of IGF1R and ROR1 CAR T cells." (PMID 26173023, 2015). "Our preclinical data suggest that IGF1R CAR T cells mounted more potent anti-sarcoma activity than ROR1 CAR T cells in vivo." (PMID 26173023, 2015). "We found that both lymphocytes and monocytes expressed lower levels of cell surface IGF1R, resulting a low level of recognition by IGF1R CAR T cells compared to sarcoma cell lines." (PMID 26173023, 2015). "Recent clinical trials have combined anti-IGF1R antibody with mammalian target of rapamycin (mTOR) inhibitors after in vitro and in vivo studies combining the two agents in sarcoma cells demonstrated decreased activation of pAKT." (PMID 25170759, 2014). "NVP-AEW541 (Novartis AG, Basel, Switzerland), an orally available, IGF1R-specific TKI, inhibited IGF1R signaling in tumor xenografts and significantly reduced the growth of IGF1R-driven sarcomas." (PMID 24904527, 2014).